IL4 (interleukin 4)
Diseases named in the same sentence as IL4 in open-access papers (continued):
Sharing a sentence is not in itself a finding about the gene and the disease.
helminth infection (continued). "Our results provide the first evidence in humans, albeit indirect, that an immunologic milieu rich in IL-4, such as seen in a helminth infection, may contribute to enhanced T cell memory against a bystander antigens, such as those encountered in malaria." (PMID 29449839, 2017). "Furthermore, we have previously reported a subset of Th hybrid cells expressing both transcription factors T-bet and GATA-3, as well as producing IFN-γ and IL-4 at intermediate levels during helminth infections." (PMID 28791259, 2017). "The finding that some helminth infections also lead to recruitment of blood monocytes and that monocyte-recruited MΦ show marked disparity in the transcriptional response to recombinant interleukin 4 (IL-4) as compared to tissue resident MΦ, suggests important functional differences." (PMID 28334040, 2017). "In the process of M2 polarization and helminth infection, the immune response of the host to helminth infections is strikingly dominated by a Th2 response with a significant production of IL-4, IL-10, IL-13, and the STAT3/STAT6 signaling pathways have been detected." (PMID 28983296, 2017). "During helminth infection, local IL-4-dependent proliferation of macrophages in the tissues has been shown to require an intact Rag locus, indicating a role for B and/or T lymphocytes; it is plausible that in this model, T cells drive macrophage proliferation through production of IL-4." (PMID 27923070, 2016). "Indeed, IL-4 and M-CSF seem to act in synergy during helminth infections allowing macrophages to expand beyond their homeostatic levels." (PMID 27966637, 2016). "Helminth infections in human host cause an immune response associated with elevated levels of IgE, tissue eosinophilia and mastocytosis, and with the presence of CD4+ T cells that preferentially produce IL-4, IL-5, and IL-13." (PMID 27980457, 2016). "Similarly, in vitro derived Th1 cells can be converted to IL-4-producing Th2 cells 7, and T cells with both Th1 and Th2 characteristics can be found during helminth infection 8,9." (PMID 24578067, 2014). "After helminthic infection, IgE production is regulated by both IL4 and IFNγ." (PMID 25415191, 2014). "On the other hand, anti-inflammatory/Th2 cytokines IL-4 and IL-10 may either be upregulated by previous helminthic infection, or as a homeostatic mechanism to buffer both production and effects of pro-inflammatory cytokines." (PMID 25303100, 2014). "The source of IL-4 (or IL-13) that drives macrophage proliferation during helminth infection is likely to vary with tissue and stage of infection 6 and may include mast cells, eosinophils, or innate lymphoid cells among others." (PMID 25319331, 2014). "Studies including ours showed that maternal helminth infection did not significantly associate with increased frequency of IL-4 secreting CBMCs to M. tuberculosis antigens." (PMID 24710174, 2014). "Eosinophils are a rapid source of IL-4 and IL-13 cytokines during helminth infection." (PMID 25028340, 2014). "This question became particularly intriguing when it was reported that macrophages activated by IL-4, the quintessential product of Th2 cells which tend to dominate the immune response during helminth infections, undergo a proliferative response that can result in local population expansion." (PMID 25144366, 2014). "Studies in mice have shown that the helminth induced increase in smooth muscle contractility is signaled through IL4 or IL-13, which could explain why it is a common observation with helminth infections." (PMID 24340121, 2013). "IL-4 and IL-13 are induced by injury or helminth infections." (PMID 24124601, 2013). "However, similar to the ability of IL-4 and IL-13 to induce the alternatively activated phenotype in macrophages in the context of helminth infections, fungus-induced Arg1 was also found to be at least partially dependent on IL-4Rα/STAT6." (PMID 21246055, 2011).
helminth infection (continued). "Together with our results, this could suggest a sustained expression of a limited number of cytokines, mainly IL-4, during long-term helminth infection in cattle." (PMID 20356390, 2010). "As no human studies are available indicating the importance of IL-4, and with the exact role of IL-4 in helminth infection being unknown, it would be premature to consider IL-4 as an important factor in the defense against strongyloidiasis." (PMID 16734908, 2006). "Altogether, these data along with a recent study that showed IL-4 production during helminth infection transcriptionally alters naïve CD4+ T cells, demonstrate that even after removal, cytokine may have long-term impacts on the naïve CD4+ T cell state or responsiveness to stimuli." (PMID 39866877, 2025). "IL-4 and IL-33 indeed have profound effects on the metabolism and epigenetic signature of macrophages, but whether the same pathways govern trained immunity during helminth infection requires further investigation." (PMID 36065058, 2022). "For example, IL-4 could signal through IL-4Rα to trigger specialized macrophage activation, promoting the mitigation of helminthic infection and tissue repair in the liver and lung, or reduce the production of C-reactive protein (CRP) by human primary hepatocytes." (PMID 34307393, 2021). "In general, helminth infections develop a Th2-type immune response with an increase in IL-4, IL-5, IL-13 and IL-33 cytokines, which may assist in the expulsion of worms in the lungs, but there are still no studies on the importance of the cytokine IL-33 in T. canis infection." (PMID 34324507, 2021). "GCs proliferation caused by helminth infection is mainly controlled by IL-4 and IL-13 in the Th2 immune response, but the GCs proliferation caused by Syphacia obvelata and Schistosoma mansoni infection is independent of IL-4 and IL-13." (PMID 33017020, 2020). "A precise understanding of the molecular signaling mechanisms suggests that targeting IL-13, while equally effective, preserves IL-4 signaling through the type-2 IL-4 receptor which may constitute an important safety benefit regarding immunity, especially to helminth infections." (PMID 30759882, 2019). "Furthermore, macrophage subsets can be very heterogenous (linked to their differing cellular origins) and the relative role of these subsets in the context of M(IL‐4) activation to helminth infection is unknown." (PMID 31267552, 2019). "Therefore, preferential recruitment and activation of Mmono in S. mansoni infection may indicate a requirement for a different “M(IL‐4)‐response” than helminth infections triggering Mres expansion (e.g. L. sigmodontis)." (PMID 31267552, 2019). "Furthermore, helminth infection promotes the early recruitment of the phagocytes Eos, mast cells, and basophils at the site of infections, which provide the rapid secretion of the Th2-type cytokines IL-4, IL-13, and TSLP." (PMID 29670630, 2018). "It is corroborated that Th2 immune responses which are responsible for the resistance of hosts to the helminthic infection could activate TGF-β1 via producing IL-4 and IL-13 and TGF-β signaling pathway, and the latter in turn acts as a prominent mediator in fibrosis." (PMID 28151995, 2017). "As helminth infections can usually induce Th2-dominated immune responses and iNKT cells can rapidly produce copious amounts of various cytokines including interleukin-4 (IL-4), these cells might be important players in the initial steps leading to Th2 responses during helminthiasis." (PMID 27563682, 2016). "Thus, similar to viral infections where Tfh cells do not become exhausted, Tfh cells may remain functionally responsive during chronic helminth infection and maintain a source of IL-4." (PMID 23516361, 2013).
helminth infection (continued). "Our results demonstrate for the first time that intestinal goblet cell hyperplasia in response to parasitic helminth infections can occur independently of IL-4/IL-13 signalling and that intestinal nematode infections may not always induce a goblet cell response." (PMID 18373844, 2008). "Validating our expectations, for these cytokines and other T helper Th-2 cytokineslike IL-13 and IL-4, their DDI statuses were lost after treatment for helminth infection." (PMID 41174472, 2025). "On the other hand, the alternative activation of macrophages is stimulated by macrophage colony-stimulating factor (M-CSF1, CSF1), IL-4, IL-10, transforming growth factor β (TGF-β), IL-13, and fungi or helminth infections, and leads to the M2 phenotype." (PMID 37958467, 2023). "Helminth infections generally induce robust type 2 immune responses, with protective immunity mediated by TH2 cells and the cytokines they produce, including IL-4, IL-5, IL-9, and IL-13." (PMID 37789420, 2023). "Further, hypercontractility of smooth muscle cells evoked by IL-4 and IL-13 was shown to be dependent on STAT6 in helminth infection." (PMID 37018382, 2023). "When T. gondii infection precedes helminth infection, a decrease in the expression of the transcription factor GATA3, in the production of IL-4, IL-13, as well as an increase in the production of IFN-γ by CD4+ T cells is observed." (PMID 35113966, 2022). "During helminth infections, another AP-1 family molecule, basic leucine zipper ATF-like transcription factor (BATF), induces IL-4 and IL-13 in ILC2s32." (PMID 36109558, 2022). "It is known that IL-4/IL-13-mediated STAT6 signaling plays a central role in promoting tuft and goblet cell hyperplasia in the small intestine during helminth infection." (PMID 36232438, 2022). "Conversely, in mice, helminth infection tends to reduce EAE severity by curtailing IFN-γ, IL-17, and IL-12 expression and enhancing IL-4 production via STAT6 signaling." (PMID 35113966, 2022). "It has been shown that during helminth infection, IL-4-producing CD4+ T cells in reactive lymph nodes have the phenotypic characteristics of Tfh cells, suggesting that these IL-4-producing cells are indeed Tfh cells." (PMID 33717120, 2021). "It has been demonstrated that stimuli such as CSF-1, IL-4, IL-10, TGF-β, IL-13, fungi, and helminth infections favor M2 subpopulation polarization, delivering IL-10 in high concentrations, and IL-12 in low amounts." (PMID 32258161, 2020). "In conclusion, using a natural murine helminth infection system to model chronic human helminth infection, we have identified an important and previously unappreciated role for ILC2-derived IL-4 for TH2 cell differentiation in vitro and in vivo." (PMID 26883724, 2016). "After the effect of LTBI and LTB-helminth co-infection was evaluated, study participants were categorized based on helminth infection and the median frequency of IFN-γ and IL-4 secreting CBMCs was also compared." (PMID 24710174, 2014). "A fraction of the activated, CD44hi T cells generated in chronic helminth infection upregulated CD200R and these cells were specifically increased in expression of IL-4/eGFP." (PMID 22496920, 2012). "Following helminth infection activated CD200R+ CD4 T cells accumulated substantially and contained IL-4 secreting effector cells." (PMID 22496920, 2012). "Similarly, we can test the predicted different response of knocking out IL4 in helminth and bacteria-helminth co-infection, specifically, whether clearance is higher than in un-manipulated individuals in single helminth infection and lower than in un-manipulated co-infected hosts." (PMID 22253585, 2012). "Of note, while germ free mice were also reported in another study to not have altered naïve CD4+ T cell subsets, helminth infection led to the emergence of a new IL-4 induced cluster in the naïve CD4+ T cell compartment." (PMID 39866877, 2025).
helminth infection (continued). "Only when the effects of both IL-10 and IL-4 are blocked does prophylactic helminth infection fail to restrict disease progression in nonobese diabetic mice." (PMID 38277692, 2024). "Helminth infection did not augment the generation of IL-4 or TGF-β by T cells within MLNs in the absence of IL-4Rα expression, narrowing down Th2-dependent TGF-β generation into a T cell–intrinsic regulatory circuit or developmental pathway." (PMID 37294277, 2023). "In helminth infection, macrophages are activated into different inflammatory states, including classically activated macrophages (M1) induced by lipopolysaccharide (LPS) and IFN-γ and alternatively activated macrophages (M2) induced by IL-4 and IL-13." (PMID 37705099, 2023). "Thus, helminth infection attenuated the Th17 response to MINCLE-dependent immunization in an organ- and adjuvant-specific manner via the Th2 cytokines IL-4/IL-13." (PMID 36753434, 2023). "The spleen T cells from mice immunized with irradiated S. mansoni cercariae and acquired protection against S. mansoni infection strongly reacted to SmCRT with IL-4 production, indicating that CRT is able to induce a Th2 response and protective immune effect during helminth infections." (PMID 36288020, 2022). "In contrast, when helminth infection precedes T. gondii infection, mice display a defective IFN-γ and IL-12 production by CD8+ T cells and cDC1, correlated with an increased IL-4 and IL-10 production leading to an enhanced T. gondii cyst load in the brain of coinfected mice." (PMID 35113966, 2022). "Single cell transcriptome and chromatin accessibility were subsequently used to identify unique gene sets, regulatory regions, and transcription factor binding sites that discriminate between IFN-gamma+ and IL-4+ CD4+ T cells as well as Th and Tfh subsets responding to helminth infection." (PMID 34106992, 2021). "In IL-4 stimulated macrophages, KDM6B-mediated H3K27me3 demethylation increases the expression of M2 marker genes 32, and KDM6B is required for M2 polarization during helminth infection." (PMID 34093857, 2021). "The data herein revealed that the responding pool of IL-4+ CD4+ T cells in the lung and lymph nodes after helminth infection represented distinct populations based on their unique gene expression and chromatin accessibility profiles, but shared a common TCR repertoire and overall antigen reactivity." (PMID 34106992, 2021). "Shared TCRs with common antigen specificities among IL-4-competent CD4+ T cells in both the lung and lung-draining lymph nodes after helminth infection are intriguing when placed in the context of our understanding of Tfh and Th2 cell fate choice during N. brasiliensis infection." (PMID 34106992, 2021). "Th2, Tregs, and the immunoregulatory cytokines they produce (such as interleukin-4 [IL4], IL10, and TGFβ) generated during helminth infection may act as potent inhibitors of the Th1 responses which are required for immunity against Mtb infection." (PMID 32498074, 2020). "Notably, anti-CTLA-4 mAb administration also induced an increase in the Th2 cytokines IL-4 and IL-5, supporting both that Tregs mediate schistosomiasis pathogenesis, and that CTLA-4 regulates the Th2 response to worm infection." (PMID 31134084, 2019). "The role of CD4+ and CD8+ T cell subset distribution and the association between memory T cell subsets and the common γc cytokines (IL-2, IL-4, IL-7, IL-9 and IL-15) in helminth infections has not been explored well." (PMID 29795573, 2018). "Helminth infections are typically characterized by the activation and expansion of CD4+ T helper 2 (Th2) cells, which express the transcription factor GATA-3 and secrete interleukin (IL)-4, IL-5, IL-9, and IL-13, leading to IgG1 and IgE antibody production." (PMID 28791259, 2017).
helminth infection (continued). "In conclusion, during a helminth infection that strongly polarizes the macrophages towards M(IL-4/IL-13), the lack of E-cadherin in these cells is not sufficient to alter their activation state and to have an impact on the outcome of the disease." (PMID 26226941, 2015). "IL-4 and IL-13 were shown previously to induce the expression of macrophage IGF-1 and coincident expression of type 2 cytokines and IGF-1 was demonstrated in experimental helminth infection." (PMID 24967908, 2014). "IL-13 and/or IL-4, which both use the IL-4Rα chain, are also central to resistance against many if not most helminth infections." (PMID 25028340, 2014). "Brugia malayi and Ancylostoma ceylanicum express homologues of the mammalian cytokine macrophage migration inhibitory factor (MIF), and in a Th2 environment, such as that activated by helminth infection, Brugia MIF synergises with IL-4 to induce the development of regulatory M2 macrophages." (PMID 23875042, 2013). "Neither did we expect to find that B. bronchiseptica infection in the lungs was not significantly altered by the concurrent helminth infection, despite the increase in local IL4 expression observed in both the simulations and the experiment." (PMID 22253585, 2012). "Thus, helminth infection promotes survival of recipient T cells in the spleen and MLNs in WT but not IL-4−/−, STAT6−/−, or IL-4Rα−/− BMT recipient mice when they receive WT C57BL/6 donor cells." (PMID 37294277, 2023). "We next tested a large cohort of BMT mice for CD3 and H2b expression, discovering that in WT mice a significant portion of CD3+ cells did not stain for H2b− following helminth infection but that almost all CD3+ cells from IL-4−/−, STAT6−/−, or IL-4Rα−/− BMT recipients did." (PMID 37294277, 2023). "However, the effects of helminth infection on common γc cytokine—IL-2, IL-4, IL-7, IL-9 and IL-15- levels have not been explored in Ss infection." (PMID 29795573, 2018). "However, although IL-4 is a master cytokine in driving TH2 immunity, the early cellular sources of IL-4 in helminth infection are less well defined and may involve accessory cells." (PMID 29491349, 2018). "However, because IL-4R-independent AAMφ differentiation has also been demonstrated in helminth infections, we examined Mφ development in either Severe-combined (SCID; no functional T or B cells) or IL-4Rα deficient (IL-4/IL-13 non-responsive) BALB/c mice." (PMID 29547639, 2018). "Finally, although CD4+ TRM cells can produce IFNγ/IL-17, and IL-4/IL-13 following helminth infection, their production of IL-10 has not previously been reported." (PMID 25974019, 2015). "Eosinophils are a rapid source of type 2 cytokines during helminth infection, and while eosinophil-derived IL-4 may not be essential for parasite killing, it may well be involved in repair following helminth migration." (PMID 25028340, 2014). "Interestingly, it was found that N. brasiliensis, a mouse model for GI helminth infection that passes through the lungs, impairs ability to control MTB infection, and that this effect was mediated by IL-4 signaling of alternatively activated (M2 type) macrophages." (PMID 24009607, 2013). "Furthermore, IL-4 as well as IL-13 could potently induce liver fibrosis which inhibited liver injuries due to accumulated Th1 like responses (such as TNF-α and IFN-γ) at the early stages of helminthic infection." (PMID 33489026, 2020). "In contrast, helminth infection did not reduce Th1/Th17 induction by TDB in draining peripheral lymph nodes, where IL-4 levels were unaltered." (PMID 36753434, 2023). "In contrast, in uninfected mice whose ability to upregulate Th2 signaling is impaired (IL-4−/−, STAT6−/−, or IL-4Rα−/− genotype), these numbers remained low and did not rise above baseline levels after helminth infection." (PMID 37294277, 2023).
helminth infection (continued). "The cytokine profile also confirmed that rTsPmy-pulsed DCs stimulated T. spiralis-infected mouse CD4+ cells to secrete IL-4, IL-10, TGF-β and IL-17A, but not IFN-γ, consistent with the Th2-skewed immune response induced by helminth infections." (PMID 27809931, 2016). "To confirm whether type 2 cytokines IL-4, IL-5, IL-9, and IL-13 contributed to helminth-induced protection against TNF-α and IFN-γ shock, we compared the levels of cytokines in the presence or absence of the helminth infection." (PMID 38727220, 2024).